AGR2 (anterior gradient 2, protein disulphide isomerase family member)
Diseases named in the same sentence as AGR2 in open-access papers (continued):
Sharing a sentence is not in itself a finding about the gene and the disease.
tumor (continued). "We validated the negative correlation between AGR2 primary tumor mRNA expression levels and disease-specific survival using data from a larger cohort of women with available information for confounder-adjustment by a variety of potential clinical and molecular confounders." (PMID 29796176, 2018). "Since cancer cells secrete AGR2 while normal cells do not, its measurement in body fluids could be used to indicate tumor presence." (PMID 26894971, 2016). "Benign tissue (NP) media contained no AGR2 in contrast to tumor tissue (CP) media." (PMID 27283903, 2016). "AGR-2 was over-expressed significantly (p<0.05) when compared to PC3 cells cultured in regular medium, suggesting AGR-2 might be required for initial adaptation of metastatic tumor cells to the new microenvironment." (PMID 24587138, 2014). "In addition, SNU-478 cells expressing AGR2-shRNA failed to form detectable tumor xenografts in nude mice, whereas control cells formed tumors with an average size of 179 ± 84 mm3 in 3 weeks." (PMID 25367337, 2014). "Moreover, within the ERα-negative group of tumours, staining for AGR2 was positively correlated with staining for PgR." (PMID 16598187, 2006). "An additional explanation for the differential prognostic impact of AGR2 on ERα-positive and ERα-negative subgroups of tumours may relate to the treatment received by these patients." (PMID 16598187, 2006). "Interestingly, extracellular AGR2 is not only clinically relevant in human tumors, but also significantly correlated with malignant mammary tumor (MMT) progression (P = 0.0007), distant tumor metastasis (P = 0.002) and poor overall survival (P = 0.0158) in dogs." (PMID 37197416, 2023). "In addition, AGR2 may also induce the expression of lactate dehydrogenase A (LDHA), phosphoglycerate kinase 1 (PGK1), kallikrein 2 (HK2) and enolase 1α (ENO1) through the MUC1/HIF-α pathway, thus induce glycolysis of cancer cells, promote cell proliferation, migration, invasion and tumor growth." (PMID 37197416, 2023). "AGR2-AXXA mutant, in the ECM of AGR2-depleted organoids, did not restore the formation of tumor organoids." (PMID 27240165, 2016). "A previous study on the effect of AGR2 overexpression on drug resistance also found ADAMTS6 expression to be reduced in NSCLC; however, the experiment did not specify the histological subtype of the studied tumor." (PMID 39940703, 2025). "In addition, AGR2 expression in SNU-869 cells did not increase anchorage-independent growth, drug resistance and formation of tumor xenograft significantly." (PMID 25367337, 2014). "However, the non-genetic gain-of-function alterations, acquired by overexpression and non-canonical localizations of AGR2 and AGR3 proteins, may be pivotal for tumour development and progression." (PMID 35857928, 2022).
cancer (168 papers, 2003 to 2026). A tumor composed of atypical neoplastic, often pleomorphic cells that invade other tissues. "AGR2 is a disulfide isomerase located in the endoplasmic reticulum, involved in protein folding, and has been implicated in cancer initiation, progression, and resistance to therapy." (PMID 41011271, 2025). "AGR2 and ERp44 loss-of-function experiments partially mimicked the effects of DDAs on cancer cells, and DDAs were found to disrupt disulfide-mediated AGR2 dimerization, as well as disulfide bonding between ERp44 or PDIA1 and their client proteins." (PMID 40867591, 2025). "A potential mechanism underlying ETV’s ability to reduce cancer cell viability is the inhibition of anterior gradient protein 2 homolog (AGR2)." (PMID 41011271, 2025). "AGR2 has gained substantial attention in cancer-associated processes and is one of the most studied proteins from the PDI family in relation to cancer." (PMID 39300184, 2024). "In humans, AGR2 expression is up-regulated in several cancers and is linked to increased progression and metastatic spread." (PMID 39727484, 2024). "Altered expression of AGR2 has been implicated with several signal transduction pathways and cell functions related to cancer initiation, progression, and metastasis." (PMID 39533806, 2024). "AGR2 has been implicated in tumorigenesis, with overexpression observed in multiple cancers, including prostate, lung, stomach, ovarian, pancreatic, oesophageal, and head and neck cancers." (PMID 39300184, 2024). "By identifying drugs that specifically target AGR2 or inhibit endoplasmic reticulum stress, their efficacy in reversing cancer or increasing cancer cell susceptibility can be enhanced." (PMID 39062458, 2024). "It was shown that extracellular AGR2 promotes epithelial morphogenesis and tumorigenesis by disrupting cell–cell contact, disrupting basal laminin and activating fibroblast-associated cancer invasion." (PMID 37175601, 2023). "The associations we noticed between AGR2 gene expression and that of a large series of genes reveal in contrast several important features in relation to oncogenesis and cancer progression." (PMID 35857928, 2022). "In the two gene clusters, some genes associated with tumorigenesis and cancer progression, such as AGR2, MMP7, LXN, PIGR, and CRABP2, were identified." (PMID 36712886, 2022). "Our study provides a comprehensive insight into the protein–protein interaction network of AGR2 by identifying functionally relevant proteins and related cellular and biochemical pathways associated with the role of AGR2 in cancer cells." (PMID 34929376, 2022). "Similar results were obtained for AGR3 with a lower number of cancer genes whose CNVs were associated with AGR3 than with AGR2 expression." (PMID 35857928, 2022). "Relationships of AGR2/3 expression with whole-genome mRNA expression and cancer features (i.e. mutations and CNVs of oncogenes and tumour suppressor genes (TSG)) were established using the CCLE and TCGA databases." (PMID 35857928, 2022). "Conversely, the upper region associated with factor 11, that includes genes such as AGR2, which is over-expressed in low-grade cancer and PIN lesions." (PMID 34638322, 2021). "A previous report showed that several distinct splice variants of AGR2 were present in cancer lines, tissue biopsies, and urine exosomes." (PMID 33413231, 2021).
cancer (continued). "While AGR2-201 and AGR2-203 isoforms encode functional proteins and are expressed in cancers, AGR2-202 is weakly expressed across cancers." (PMID 33005802, 2020). "Overexpression of AGR2 has been linked to the proliferation, migration and invasion of several cancers." (PMID 33167358, 2020). "High AGR2 expression, as well as its secretion into body fluids, was reported in many cancer types and associated with pro‐tumorigenic phenotype and poor patient outcome." (PMID 31040128, 2019). "Studies that show a high expression level of AGR2, and associate the protein expression with the resilience to chemotherapeutic treatments or with poor cancer survival, are reported." (PMID 31247903, 2019). "Due to the large amount of evidence that links AGR2 with cancer initiation and progression and eAGR2 to various diagnostic or prognostic metrics, we focused on the identification of novel peptides that can specifically bind AGR2." (PMID 29937991, 2018). "A number of reports have demonstrated that tissue expression of AGR2 is a diagnostic biomarker capable of distinguishing normal from cancer cohorts in bladder, and lung adenocarcinomas." (PMID 29937991, 2018). "The first paradigm holds that the normal cell adhesion associated function of AGR2 is exploited as an oncogenic signal in cancer development." (PMID 29339412, 2018). "This third paradigm, therefore, claims that the ability of AGR2 to mediate oncogenic growth is linked to its ability to catalyze the maturation of cysteine-rich receptors that play cancer associated functions in vivo." (PMID 29339412, 2018). "Subsequent data highlighting a role for AGR2 in mammalian cancer-associated cell adhesion provided the link between the normal developmental function of AGR2 and its oncogenic activity." (PMID 29339412, 2018). "We sought to ascertain a potential mechanism leading to decreased viability of cells upon exposure to H10 by examining cancer related pathways that have been linked with AGR2." (PMID 29937991, 2018). "During these studies, a clinical proteomics analysis using resected biopsies from patients with esophageal adenocarcinoma identified AGR2 and EpCAM as highly expressed in primary adenocarcinoma as well as cancer-associated lymph nodes." (PMID 29339412, 2018). "AGR2 protein was shown to regulate several cancer-associated processes including cellular proliferation, survival and drug resistance." (PMID 28810836, 2017). "Anterior gradient 2 (AGR2) is a cancer-associated secreted protein found predominantly in adenocarcinomas." (PMID 26894971, 2016). "It has been reported that overexpression of AGR2 is associated with poor differentiation, deep invasion, and lymph node metastasis in several types of cancer." (PMID 24717913, 2014). "AGR2 is a disulfide isomerase over-expressed in several human carcinomas and recently linked to endoplasmic reticulum (ER) stress." (PMID 24976026, 2014). "AGR2 has been implicated in cancer pathogenesis and has been found to be up-regulated in multiple human cancers, including breast, lung, and prostate." (PMID 21144054, 2010). "Several genes that encode these proteins were upregulated in the CD26+ cancer cells: AGR2, BCMP11, CEACAM5/CD66e, CRISP3, KCNG3, KCNH8, LOX and NEO1." (PMID 20021671, 2009). "There is a significant association of staining of carcinomas for AGR2 with oestrogen receptor α (ERα) staining and with low histological grade (both Fisher's Exact test P<0.0001)." (PMID 16598187, 2006). "Moreover, AGR2 dysregulation has been implicated in certain disease processes, such as cancer progression and drug resistance." (PMID 36899352, 2023). "AGR2 protein exists in an equilibrium between homodimeric and monomeric states, with the first state dominating in physiologically normal conditions and the balance shifting to the monomer in cancer-associated conditions." (PMID 37175601, 2023). "In different cancer types, high AGR2 expression was associated with poor patients' prognosis." (PMID 35689436, 2022).
cancer (continued). "Our result demonstrate that AGR2 causes the re-arrangement of actin stress fibers, highlighting that the effects of AGR2 on the adhesion of cancer cells is mediated (at least partially) via the role of β-DG as a platform for both the cytoskeletal network and focal adhesion complex." (PMID 33717413, 2021). "Presumably over-expressed AGR2 up-regulates β-DG post-transcriptionally and facilitates its trafficking, which then causes re-arrangement of the cytoskeletal network, which plays a role in the adhesion and invasion of cancer cells." (PMID 33717413, 2021). "AGR2 was also required for delivery of EGFR to the plasma membrane that may contribute to oncogenic function in cancers since AGR2-deficient cells showed immature and cytoplasmic staining of EGFR." (PMID 33005802, 2020). "The association of AGR2 with drug resistance was also studied in other cancers." (PMID 31247903, 2019). "We wanted to test if AGR2 is a cancer-specific tumor-associated antigen." (PMID 31303962, 2019). "The present review aims to determine how the metastatic-linked protein anterior gradient homologue 2 (AGR2) operates to affect cancer progression, and to identify associated potential diagnostic, prognostic and therapeutic biomarkers, particularly in central nervous system (CNS) tumors." (PMID 31247903, 2019). "The association of AGR2 with multiple cancer-related pathways, particularly the metastatic pathway, combined with its nature to be secreted into the extracellular space makes it a tantalizing non-invasive cancer biomarker." (PMID 31247903, 2019). "To study whether the method can detect an association of AGR2 and EpCAM, we required the use of cancer cell lines where AGR2 and EpCAM show mutual expression and where their assembly pathways are presumably intact." (PMID 29339412, 2018). "Induction of EMT was associated with decreased AGR2 along with changes in cellular morphology, actin reorganization, inhibition of E-cadherin and induction of the mesenchymal markers vimentin and N-cadherin in various cancer cell lines." (PMID 28810836, 2017). "The PCD-inducing property of AGR2 may be responsible for the irreversible loss of body mass in cancer cachexia." (PMID 27283903, 2016). "Alternatively, overexpression of AGR2 in cancer cells could saturate the KDEL receptors in the ER causing the excess protein molecules to be exported." (PMID 26894971, 2016). "Thus AGR proteins have growth promoting effects, a property that is linked to the role of AGR2 in cancer development and metastasis of several tumor types." (PMID 25111734, 2014). "Using a PCR-based approach, we could show that in addition to the wild-type (AGRwt long and short) transcripts, five other AGR2 splice variants (SV) (referred to as AGR2 SV-C, -E, -F, -G and -H) were present in cancer cell lines." (PMID 25237833, 2014). "Besides, AGR2 is widely implicated in human diseases, particularly in cancer." (PMID 33005802, 2020). "However, the underlying mechanism and biological implication of AGR2, especially in cancer stem cell and epithelial mesenchymal transition, remain unclear." (PMID 25871396, 2015). "Therefore, these diseases might generate a potential link to increased cancer risk due to the IGF-1 induction of AGR2." (PMID 25956506, 2015). "Although cell death was observed in both PC3Control cells and PC3AGR−2sh cells, PC3AGR−2sh cells survived the TRAIL challenge significantly better than the PC3Control cells suggesting loss of AGR-2 might be associated with development of anoikis resistance in malignant tumor cells." (PMID 24587138, 2014). "Some of the documented pro-cancer effects of AGR2 relate to its ER-localized disulfide isomerase activity, which depends on its active site thioredoxin Cys residue and the KTEL C-terminal ER retention motif." (PMID 40867591, 2025).
cancer (continued). "A second-generation biotinylated DDA identified the PDIs ERp44, PDIA1, and AGR2 as the major DDA targets in cancer cells." (PMID 40867591, 2025). "Gene set enrichment analysis highlighted enhanced H6PD and AGR2 expression in pathways such as fatty acid metabolism and glycolysis that have key roles in cancer progression and deserve special attention in further research." (PMID 40281598, 2025). "Several observations suggest that AGR2 plays a role in cancer progression, including its necessity for EGFR presentation at the cell surface, its upregulation in Estrogen Receptor-positive breast cancers, and its ability to transform colonic epithelial cells." (PMID 40867591, 2025). "Previous research has demonstrated that AGR2 is highly expressed in various human cancers and plays a functional role in promoting the progression and metastasis of adenocarcinomas." (PMID 38951833, 2024). "The availability of large subsets of tumors from various important cancer entities enabled us to also address the clinical/prognostic relevance of AGR2 expression in diverse cancers." (PMID 39533806, 2024). "Understanding the mechanisms underlying the AGR2-controlled release of 14-3-3ε and α-actinin 4 in response to stress conditions will contribute to the refinement of AGR2-targeting therapeutic strategies for cancers." (PMID 38822246, 2024). "This comprehensive review delves into the established functions and expression patterns of AGR2, emphasizing its pivotal role in cancer progression, particularly in hepatobiliary and pancreatic malignancies." (PMID 39062458, 2024). "Further research in this field is essential to enhance the understanding of the complex interactions between AGR2, the immune microenvironment, and treatment outcomes in cancer patients." (PMID 39062458, 2024). "If AGR2 secretion and impact on cell migration is limited to cancer cells, then the therapeutic MAbs we present herein potentially target a cancer-specific mechanism that should be given high priority in PDAC." (PMID 39727484, 2024). "AGR2 disruption affects normal mucin production, potentially influencing cancer invasion by altering the intestinal mucosal flora." (PMID 39062458, 2024). "Dendritic cells featuring AGR2 as a potent antigen are currently harnessed to bolster cancer immunotherapy by activating AGR2-specific T cells to combat cancer cells." (PMID 39062458, 2024). "AGR2 displays the following expression pattern: highest in G3 cancer cells, 10-fold lower in G4 cancer cells, high in prostatic intraepithelial neoplasia, and absent in luminal cells." (PMID 38595814, 2024). "Next, we investigated the role of AGR2 in regulating the release of 14-3-3ε and α-actinin 4 during specific cancer progression-related stress conditions, including the unfolded protein response (UPR)-induced ER stress and autophagy." (PMID 38822246, 2024). "In conclusion, cancer drug resistance significantly impacts cancer prognosis, highlighting the importance of further investigations into the link between AGR2 and drug resistance." (PMID 39062458, 2024). "Closed monoclonal antibodies against AGR2 and C4.4A developed in mouse studies have shown reduced cancer invasiveness." (PMID 39062458, 2024). "Understanding the diverse functions of AGR2 underscores its essential role in preserving organismal homeostasis while contributing to cancer invasion through imbalances in self-expression." (PMID 39062458, 2024). "Understanding the proteins that regulate AGR2 expression is crucial in unraveling the mechanisms of cancer development." (PMID 39062458, 2024). "AGR2, thought to play a role in protein folding, is expressed highly in many cancers, promoting angiogenesis, enhancing metastasis and tumor progression." (PMID 39082334, 2024).